GMNC (geminin coiled-coil domain containing)
Description:
Regulator of DNA replication. Promotes initiation of chromosomal DNA replication by mediating TOPBP1- and CDK2-dependent recruitment of CDC45L onto replication origins (By similarity).
Synonyms: GEMC1
Tractability: Antibody: its Gene Ontology location is reachable by antibodies, with medium confidence.
Gene: Protein-coding gene on chromosome 3 (190,852,737 to 190,892,429, reverse strand). Ensembl gene ENSG00000205835.
Subcellular location: Nucleus
Gene Ontology:
Molecular function: protein binding; chromatin binding; transcription coregulator activity; transcription coactivator activity
Biological process: regulation of DNA-templated DNA replication initiation; DNA replication; positive regulation of transcription by RNA polymerase II
Cellular component: nucleus
Genetic constraint (gnomAD): Loss-of-function variants: 13 observed, 23.44 expected, observed/expected ratio (o/e) 0.55, 90% interval 0.36 to 0.88. The upper end of that interval is the gene's LOEUF score, 0.88, which puts it in group 3 of 6, group 1 being the genes least tolerant of losing a copy. Missense variants: 300 observed, 314.67 expected, observed/expected ratio (o/e) 0.95, 90% interval 0.87 to 1.05. Synonymous variants: 122 observed, 118.01 expected, observed/expected ratio (o/e) 1.03, 90% interval 0.89 to 1.2.
Homologues: Orthologues: chimpanzee GMNC (99% identical), dog GMNC (87% identical), pig GMNC (86% identical), rabbit GMNC (85% identical), mouse Gmnc (78% identical), rat Gmnc (76% identical), guinea pig GMNC (75% identical), macaque GMNC (75% identical), tropical clawed frog gmnc (52% identical), zebrafish gmnc (42% identical), Drosophila melanogaster geminin (5% identical). Paralogues in human: MCIDAS (22% identical), GMNN (11% identical).
Diseases named in the same sentence as GMNC in open-access papers:
GMNC is named in the same sentence as 7 diseases in open-access papers, as found by Europe PMC text mining. Sharing a sentence is not in itself a finding about the gene and the disease. The quoted sentences say what the papers report.
tumor (2 papers, 2022 to 2025). "In agreement, among 11 cases of human CPCs examined, most displayed significantly reduced or complete loss of GMNC expression, and GMNC expression was heterogeneous and only detected in a subpopulation of tumor cells." (PMID 35322202, 2022). "We found that the expression of 9 DE-ceRNAs were significantly different between tumor tissues and normal tissues, including the upregulated H19, HOTAIR, miR222, miR148a, PCDHGB4, GMNC and HMGA2 and the downregulated LRP2 and MBP in tumors." (PMID 40351420, 2025). "NOTCH suppresses multiciliation in tumor cells by inhibiting the expression of GMNC and MCIDAS, while Gmnc-Mcidas overexpression rescues multiciliation defects and suppresses tumor cell proliferation." (PMID 35322202, 2022). "In contrast, Gmnc loss failed to accelerate tumor development in Lcre;p53cko;Rbcko;Gmnccko animals, indicating that GMNC does not play a clear tumor suppressive role." (PMID 35322202, 2022).
GMNC also shares sentences with these, for which no sentence is quoted: Alzheimer disease (1 paper); congenital hydrocephalus (1); Hydrocephalus (1); infection (1); infertile (1); intracranial hemorrhage (1).